IFNG (interferon gamma)
Diseases named in the same sentence as IFNG in open-access papers (continued):
Sharing a sentence is not in itself a finding about the gene and the disease.
tumor (continued). "The upregulation of tumor cell adaptive immune resistance pathways is related to the production of interferon‐gamma (IFN‐γ) by CD8+ T cells in TIME." (PMID 37850692, 2024). "The signaling pathway of the cytokine IFNγ in tumor cells is influenced by the E3 ubiquitin ligase STUB1." (PMID 39223632, 2024). "The matured tumor antigen-pulsed DC vaccine exerted a significant tumor suppression correlated with the generation of antigen-specific IFNγ-producing lymphocytes in the spleen." (PMID 38646546, 2024). "Further analyses showed that the expression of IFNG and CXCR5 were significantly associated with tumor size (p = 0.032 and p = 0.047, respectively), and their expression was lower in invading tumors (T4)." (PMID 39001456, 2024). "A second relevant mechanism of the NK-cell-mediated anti-tumor response is the secretion of cytokines and chemokines, in particular interferon-gamma (IFNγ), which can increase antigen presentation and activate other immune cells." (PMID 39563446, 2024). "This resulted in a decrease in regulatory T cells and a decrease in tumor-infiltrating myeloid-derived suppressor cells, along with an increase in granzyme B and interferon-gamma (IFN-γ), and effector T-cell activation." (PMID 38256070, 2024). "Interferon-gamma (IFNγ), produced by natural killer (NK) cells and T cells during tumor rejection, plays a critical role in tumor immunity by directly inducing apoptosis or autophagy in cancer cells." (PMID 39595619, 2024). "Tumor cells and M0 MDMs were co-cultured for 48 h prior to the addition of activated autologous T cells resuspended in media containing IFNG neutralizing antibody or IgG isotype control antibody, or PBS vehicle." (PMID 39414902, 2024). "We observed a positive correlation in tumour cells between the expression of gene sets related to antigen processing presentation, response to IFNγ and leukocyte‐mediated cytotoxicity, which was strongest in the PI3K/mTORi+PD‐1i‐tumours." (PMID 38711203, 2024). "This was associated with increased expression of IFNγ and granzyme B by CD4+ and CD8+ T cells of tumor-bearing Ac-CD4Cre mice compared to wt littermates." (PMID 38919612, 2024). "We analyzed and found that CD3+ T cells, NK cells, IFNγ+CD8+ T cells were increased in the tumor tissues of these mice under ATB- Ad-E + αPD-1-B.F." (PMID 39251538, 2024). "CD8 T cells can directly eliminate tumour cells by specifically targeting components of these cells or by secreting interferon‐gamma (IFN‐γ) and tumour necrosis factor‐beta (TNF‐β), thereby activating NK cells and macrophages to eradicate tumour cells." (PMID 39248438, 2024). "First, we observed that B7-H3-CXCR2 CAR T cells produced significantly more cytokines (IFNγ and IL-2) following tumor cell target engagement." (PMID 38554158, 2024). "Of note, IFNγ can play a role in inhibiting the growth of tumor cells; however, it also plays a role in promoting full activation of different immune populations as well as MHC‐I peptide expression required for subsequent T‐cell detection and killing." (PMID 38707997, 2024). "After stimulated by IFNγ, tumor cells would express transcriptional regulator class II transactivator (CIITA), which induces the expression of MHC-II, through the JAK/STAT signaling pathway." (PMID 39105803, 2024). "Resistance is contributed by one or many of the following factors such as irreversible T-cell exhaustion, dysfunctional antigen presentation, resistance to IFNg signaling, and tumor/stroma-driven immunosuppressive environment." (PMID 38383563, 2024). "In fact, it is known that in the tumor microenvironment, IFNγ plays a dual role, regulating both antitumor and pro-tumorigenic immune responses." (PMID 39769153, 2024). "IP is expressed in tumor cells under inflammatory conditions in response to interferon-gamma (IFNγ) but is constitutively expressed in specialized antigen-presenting cells such as dendritic cells." (PMID 39116074, 2024).
tumor (continued). "The possible reasons for this dual effect of IFNγ signaling on tumor growth and development are still debated." (PMID 38396830, 2024). "IFNG is known for assisting in the prevention of neoplastic disease and is a potent activator of macrophages." (PMID 38638111, 2024). "In inflammatory conditions, Treg-specific ablation of the scaffold protein CARD11, destabilizes Tregs in tumor tissues and secretes IFNγ to decline tumor growth, revealing its primary role in the depression of anti-tumor effects." (PMID 39227959, 2024). "IFNγ, a pleiotropic cytokine produced not only by activated lymphocytes but also in response to cancer immunotherapies, has both antitumor and tumor-promoting functions." (PMID 39123403, 2024). "CD8+ cytotoxic T lymphocytes (CTLs) are the primary tumor-killing cells, which can activate themselves through T cell receptor binding to antigens presented by MHC-I molecules, expressing high levels of IFNγ, TNFα, perforin, and granzymes to kill tumor cells." (PMID 38523155, 2024). "Taken together, our results position IFNγ as a key mediator of tumor inhibition and strongly suggest that IFNγ production, rather than direct CD8+ T cell cytotoxicity, is required for therapeutic response to DCP-IL-12/FLT3L." (PMID 37996514, 2024). "To validate the role of tumor-intrinsic IFNγ signaling in antitumor immune responses uncovered in the screen, we generated Ifngr2−/− KPAR cell lines using CRISPR–Cas9." (PMID 38635884, 2024). "The combination i.t. treatment led to increased IFNγ production from splenocytes and cells isolated from the tumor draining LN." (PMID 38803496, 2024). "The activated cytotoxic CD8+ T lymphocytes then relocate to the tumour site, releasing interferon gamma, promoting eradication of the neoplastic lesion, and stimulating the formation of a long-lasting immunological memory against the tumour." (PMID 39011040, 2024). "COL11A1- and EDB-CAR T cells produced significant amounts of IFNγ in comparison to NT T cells only in the presence of antigen-positive tumor cells." (PMID 38702309, 2024). "The paper demonstrates that IFNγ obstructs cystine uptake in tumor cells, triggering lipid peroxidation and subsequent ferroptosis." (PMID 39944353, 2024). "Cytokines such as IFNγ, IFNα, and IL-2 promote anti-tumor responses in the TME, while dysregulation of cytokines produced by immune, malignant, and stromal cells are involved in the entire process of carcinogenesis and therapy response." (PMID 39507618, 2024). "It has been established that a response of at least 30% induction of a single key cytokine (e.g., IFNg) in the ex vivo tumor model is correlative with clinical responses." (PMID 39199551, 2024). "Although our findings supported the pro-inflammatory role of IFNγ signaling in tumor biology, IFNγ also has pleiotropic effects on ICB." (PMID 39105803, 2024). "We have previously demonstrated that anti-tumor CD8+ T cell responses depend on IFNγ-triggering destruction of blood vessels." (PMID 39033271, 2024). "Our findings revealed that the inhibition of Granzyme B and IFNγ by CD8 + T cells from tumor tissues was reversed upon CD155 knockdown." (PMID 38216949, 2024). "RANTES, which is associated with recruitment of cytotoxic, IFNγ-producing CD4 and CD8 T cells that interact with anti-tumor macrophages, was profoundly up-regulated, and pro-inflammatory (M1) cytokines IL-12 and IFNγ increased." (PMID 38458648, 2024). "IFNγ also suppresses the antitumor immune response, increases the metastatic potential of tumor cells, enhances angiogenesis, reduces the migration of cytotoxic T lymphocytes, and more." (PMID 38396830, 2024). "Inhibition of exosome release and TGF-β in vivo synergistically reduced tumor burden through reversing exhausted T cells and promoting the release of granzyme and interferon-gamma (IFN-γ)." (PMID 38884843, 2024).
tumor (continued). "ILC1s are potent producers of the well-established anti-tumour cytokine interferon γ (IFNγ), and exert direct cytotoxicity against cancer cells in response to the cytokine interleukin-15 (IL-15)." (PMID 38745765, 2024). "This action increases the sensitivity of tumor cells to ferroptosis and promotes tumor immunogenic death by increasing interferon-gamma (IFNγ) production and reducing lactate concentration, enhancing tumor immunogenic death." (PMID 39273090, 2024). "Splenocytes from medium-MG1-treated animals displayed a recall response against 4434 tumor cells ex vivo as measured by IFNγ release, while splenocytes isolated from large-MG1-treated animals showed no such responses." (PMID 39060020, 2024). "AML3 and AML5 showed heightened enrichment of pathways involved in anti-tumor response and lipid metabolism, including the interferon-gamma response, oxidative phosphorylation, adipogenesis, interferon-alpha response, and fatty acid metabolism pathways." (PMID 37615858, 2024). "Studies have shown that interferon-gamma (IFN-γ) secreted by immune cells can induce ferroptosis in tumor cells, and Res has been demonstrated to activate and increase the expression of IFN-γ." (PMID 38891683, 2024). "In this context, the constitutively active STAT6 drives the expression of granzyme A, granzyme B, FasL and IFNγ proteins, which can be critical to donor T cell-mediated anti-tumor (GVT) immunity." (PMID 39796136, 2024). "The kynurenine-AhR pathway directly upregulates PD-1 expression on CD8+ T cells, while interferon gamma (IFNγ) expression from activated CD8+ T cells drives further kynurenine production from tumor repopulating cells, leading to paracrine deactivation." (PMID 38339226, 2024). "The tumour-specific CD8+ T-cells also showed increased expression of IFNγ in the lung of IAV-infected tumour-bearing mice." (PMID 38271469, 2024). "Our in vivo study shows that GW501516 treatment reduces tumor-associated CD8+ T-cell activation, as evidenced by decreased proliferation and IFNγ expression." (PMID 39292167, 2024). "Compared with ADR and ISO-PLGA-ADR, the in vivo antitumor effect of TNFR2-PLGA-ADR was markedly enhanced, which was associated with a decrease of TNFR2+ Tregs and an increase of IFNγ+CD8+ cytotoxic T lymphocytes in the tumor tissue." (PMID 39247806, 2024). "Blocking IL-4, which suppresses IL-12 production, in NSCLC mouse models augmented cytokine production by CD4+ T cells activated by mregDCs, resulting in reduced tumor growth and an increased expansion of IFNγ+TNF+CD8+ T cells." (PMID 38716077, 2024). "IFNγ is a multifunctional cytokine produced not only by activated lymphocytes but also in response to cancer immunotherapies; it has both antitumor and tumor-promoting effects." (PMID 39123403, 2024). "One of the many physiological actions of IL-4 is to negatively modulate Th1 T cells, dendritic cells, and IFNγ production, facilitating tumor growth." (PMID 38607023, 2024). "Paired tumor and microbial antigens from that study were then tested in T cell cultures from patients with hepatocellular carcinoma, lung cancer, and colon cancer to confirm cross-reactivity and an IFNγ anti-tumor response." (PMID 39594997, 2024). "A study investigating IFNγ effects on NK-mediated lysis in 22 pediatric tumor cell lines, including NB, revealed varied responses to treatment, with some NB lines remaining unaffected, some developing resistance, and others becoming more sensitive." (PMID 39294470, 2024). "Despite a high number of ongoing clinical trials, this cytokine has not been approved by the FDA to treat patients with cancers, except malignant osteoporosis, possibly because of the contribution of IFNγ to tumor evasion and the induction of adverse events." (PMID 39204319, 2024). "The numbers of TILs per gram tumor secreting GzmB, IFNγ, TNFα, and IL-2 were considerably higher in both primary and secondary tumor in the hRT/lena treatment group." (PMID 38646638, 2024).
tumor (continued). "In a CD20/EGFR CAR T cell model, ICAM-1 was shown to increase in an IFNγ dependent manner and permitted tumor islet infiltration by T cells." (PMID 38786066, 2024). "These neutrophils show increased production of IFNγ and improve the tumor response to the anti-PD-1 immunotherapy pembrolizumab." (PMID 39409924, 2024). "To explore how HKDC1 regulates CD8+ T cell-dependent tumor immune evasion, we detected the mRNA levels of immune checkpoint markers in IFNγ-stimulated Hep3B cells expressing shHKDC1s or NTC." (PMID 38351096, 2024). "This process effectively activates innate immunity responses such as tumor cell death, macrophage recruiting, and IFNγ production." (PMID 38238307, 2024). "IFNγ gene signature has been reported to be positively correlated with ICIs treatment outcomes due to the ability to activate tumor microenvironment cells such as T cells and Natural killer (NK) cells." (PMID 36910641, 2023). "Our work showed that the administration of a targeted attenuated version of IFNγ can trigger the host immune response leading to tumor growth retardation." (PMID 36839699, 2023). "Single-cell sequencing indicated that IFNG was mainly expressed in T cells in the tumor microenvironment." (PMID 37154982, 2023). "Collectively, these results suggest that IFNγ produced by tumor-infiltrating T cells induced HLA-II expression on HT-29 cells required for tumor recognition by CD4 CTLs." (PMID 37185301, 2023). "Similar techniques have been presented previously by other groups, using machine learning to identify IFNγ-related mRNA profiles and the 18-gene tumor inflammation signature to predict responses to immunotherapy." (PMID 37569808, 2023). "IFNγ is a cytokine produced by activated T cells and NK cells in the tumor microenvironment and plays an important role in anti-tumor immunity." (PMID 36946842, 2023). "In line with this, CHAC1 deficiency in tumor cells impaired the infiltrations of CD8+ T cells, and expressions of IFNγ and TNFα in CD8+ T cells and CD4+ T cells that were all induced by the combination therapy." (PMID 37553341, 2023). "Consistent with this, IFNγ concentration in the tumor milieu was similar between control and CD8-IFNγRKO mice, as measured by ELISA." (PMID 36658158, 2023). "When comparing Apcmin/+;Klrk1+/+ with Apcmin/;Klrk1−/−, we observed a higher fraction of tumor-infiltrating IFNγ-high producing CD8+ T cells in Apcmin/+;Klrk1+/+ than Apcmin/+;Klrk1−/− mice." (PMID 36980678, 2023). "In summary, SNX9 KO alleviates exhaustion, increases chemoattraction, and prolongs IFNγ secretion of tumor-specific T cells." (PMID 36732507, 2023). "Neutrophils expressing TNF-related apoptosis-inducing ligand (TRAIL) displayed enhanced tumour cell killing in vitro in an IFNγ-dependent manner." (PMID 37180120, 2023). "IFNG secreted by CTLs was the putative agent which led to cell-cycle arrest and the transient reduction of tumor progression in our studied data." (PMID 37182110, 2023). "IFNγ at the tumor microenvironment is able to interfere with tumor growth either directly by inducing apoptosis and reduction of cell proliferation or by further recruitment of adaptive immune cells." (PMID 37609636, 2023). "Strikingly, we saw dose-dependent dampening of tumor cell killing with blockade of IFNγ signaling using OV90 tumors cells (left) and OVCAR3 tumor cells." (PMID 37550294, 2023). "CD56bright NK cells produce large amounts of cytokines such as interferon-gamma (IFN-γ), which can regulate other immune cells or directly affect tumor cell viability, while CD56dim NK cells are involved in direct cell-mediated cytotoxicity." (PMID 36932395, 2023). "IL10 has been shown to upregulate the production of cytotoxic enzymes and IFNγ in tumor infiltrating CD8 + T lymphocytes, thereby inducing antigen-presentation." (PMID 37259163, 2023). "B cells can promote anti-tumour immunity through the release of cytokines such as IL-12, IFNγ, granzyme B and TRAIL57." (PMID 37365284, 2023).
tumor (continued). "Although cluster 1 samples had higher scores on recognition of tumor cells, immunosuppressor features like marrow-derived suppressor cells, inhibitory molecules, and IFNG response were enriched in cluster 1 samples." (PMID 37122693, 2023). "A similar trend was observed in the relative frequencies of IFNγ+ CD4+ to IL-17A+ CD4+ T cells (Tumor 9.7% versus 5.5%; STM 8.2% versus 1.3%)." (PMID 38074634, 2023). "To obtain insights into the kinetics of the tumor-reactive T cell response, we assayed NeoAg-specific T cells via IFNγ ELISpot on days 7, 10, and 14 post tumor implantation." (PMID 37548358, 2023). "Our in vitro data suggest that SON-1210 should stimulate the expected mechanisms associated with the therapeutic efficacy of the molecule, particularly T- and NK-cell stimulation and IFNγ production, which is important for local tumor surveillance." (PMID 38250068, 2023). "Inhibition of MALT1 in tumor-bearing mice with a drug induces Treg cells to secrete the immunostimulatory cytokine IFNγ only in tumor tissue, resulting in stunted tumor growth." (PMID 37828948, 2023). "PPARγ agonist (pioglitazone) restored IFNγ production in tumor-infiltrating iNKT cells from patients and mice, and in combination with an immunostimulant (α-galactosylceramide), enforced iNKT cell-driven anti-tumor responses for prolonged animal survival." (PMID 37686465, 2023). "More importantly, the proportion of tumor-infiltrating IFNγ-expressing CD8+ CTLs was increased by 2-4 folds in TNFR2-deficient tumors, compared with those in W.T. tumors (P < 0.01-0.001)." (PMID 36923938, 2023). "Overall, IFNγ is capable of inducing anti-tumour immunity via direct action on tumour cells or indirectly through stimulating type 1 immunity." (PMID 37455828, 2023). "While γδ T cells are known to be cytotoxic to cancer cells by producing IFNγ and destroying tumor cells, there is increasing evidence that IL17-producing γδ T cells can promote tumor growth." (PMID 36968223, 2023). "IL10 is known to drive macrophage polarization towards a pro-tumor regulatory M2-like phenotype while IFNγ is known to drive macrophage polarization towards a stimulatory anti-tumor M1-like phenotype." (PMID 37654482, 2023). "Remarkably, the FMT from long-term survivors enhanced the CD8+IFNg+ T cell infiltration, reduced FoxP3+ Tregs and Ly6G/Ly6C+ MDSCs, and reduced tumor growth in the recipient mice." (PMID 37488598, 2023). "In terms of model structure, we utilized our previously developed QSP model of TNBC and incorporated an additional source of IFNγ in the tumor microenvironment." (PMID 37291190, 2023). "Subsequent analyses showed production of IFNγ and GzmB- and Perforin-dependent killing of tumor cells by tgTCR CD4+ T cells in a MHC class II-dependent manner." (PMID 37965314, 2023). "Tumor immune evasion can be facilitated not only by gene silencing or mutations in MHC‐I molecules and genes encoding IFNγ signaling pathway components in tumor cells, but also by changes in the tumor microenvironment." (PMID 37452654, 2023). "We found that combination treatment induced increased IFNγ+ T cell accumulation within the tumor center compared to control treatment." (PMID 37543621, 2023). "For instance, IFNγ promotes the activity of tumor-triggered αβ T cells and inhibits the differentiation and activation of regulatory αβ T cells." (PMID 37139603, 2023). "IFNγ induces regulatory T cell apoptosis and induces the differentiation of macrophages into the M1, pro-inflammatory phenotype, to overcome tumour progression." (PMID 39935547, 2023). "RT plus anti-TIGIT combination therapy increased the number of CD8 + T cells and the percentage of IFNγ + TNFα + CD8 + T cells in tumor tissues and TdLNs in WT mice." (PMID 35794399, 2023). "Of note, 40% of TRP-1 CD4+ T cells isolated from CD4 ACT-treated mice produced IFNγ following stimulation with tumour lysate-pulsed dendritic cells, confirming their TH1 phenotype." (PMID 37316667, 2023).